IL6 (interleukin 6)
Diseases named in the same sentence as IL6 in open-access papers (continued):
Sharing a sentence is not in itself a finding about the gene and the disease.
tumor (continued). "These cytokines have been previously found to support tumor growth (IL-6) and tumor hyper-vascularization (VEGF)." (PMID 37240536, 2023). "Next, we performed immunohistochemistry assays to detect the effects of IGF2BP3/circGNB1/miR-515-5p/miR-582-3p/XPR1/IL6 axis on tumor tissues." (PMID 37407973, 2023). "Statistically significant associations of levels of tumor markers at the time of diagnosis and death were observed for CA125, HE4, CRP, PCT and Il-6." (PMID 37373969, 2023). "Elevated levels of IL-6 have been observed in various tumor types, including colon, ovarian, pancreatic, lung, hepatocellular, breast, prostate, and multiple myeloma." (PMID 37892997, 2023). "It was established that IL-6 was highly expressed in the inflammatory and tumor microenvironment and bound to IL-6R and gp130 to form a heterohexameric complex to initiate signaling pathways and induce activation of gp130-associated JAKs." (PMID 36865551, 2023). "The tumor cells of iCCA shared common activated signaling pathways, including IL-6/STAT3, Wnt, transforming growth factor (TGF), and tumor necrosis factor (TNF)." (PMID 36980203, 2023). "Activation of P2X7 in tumor cells induces the expression of IL-6, IL-8, and MCP-1 through a Ca2+-dependent mechanism." (PMID 38273855, 2023). "Tumor cells release IL-6, inhibiting the CD34+ cell differentiation into DCs and promoting the transition of these cells to the monocytic lineage with deficient APC function." (PMID 37781367, 2023). "(E) Met-1 Kin1-NULL tumors were established via subcutaneous injection in FVB mice, with 20 μg anti-IL-6 neutralising antibody administered on Day –1, 0, 4, 8, 12, and 16 post tumor cell injection." (PMID 36883731, 2023). "Multivariate regression analysis revealed that BMI, leptin, IL-6 and reactive oxygen species were predictive factors for tumour size, lymph node stage and metastasis status in ER+ patients." (PMID 37173907, 2023). "Even IL-6 blockade in cancer patients treated with immune checkpoint blockade is viewed as a win-win strategy because combined IL-6 blockade and immune checkpoint blockade abrogates immunotherapy toxicity and promotes tumor immunity." (PMID 37114049, 2023). "Surgery has also been found to affect the number of TAMs, the level of IL-6, and the level of chemokine (C-C motif) ligand 5 (CCL5), all of which are associated with angiogenesis, cell migration, and tumor cell invasion in TNBC." (PMID 37512096, 2023). "For example, it was reported that tumor growth is reduced in IL17-/- mice, probably due to the lost capacity of IL-17 to promote tumor growth via the IL-6/STAT3 pathway." (PMID 37460545, 2023). "IL6, a pro-inflammatory cytokine secreted locally and systematically by adipocytes, is significant for tumor development, as high plasma levels correlate with poorer overall survival of BC patients." (PMID 37445860, 2023). "Tumor production of cytokines such as IL-1 and IL-6 can induce neutrophilia, with higher circulating neutrophil counts at baseline theoretically corresponding with an increased burden of disease." (PMID 37333401, 2023). "IL‐6 is produced by multiple cell lineages in the tumor microenvironment and exerts its oncogenic effects via both autocrine and paracrine mechanisms." (PMID 37696858, 2023). "Deletion of IL‐6 from CHX207 cancer cells completely protected CHX207IL6KO‐tumour‐bearing mice from CAC." (PMID 36351437, 2023). "Tumor-promoting cytokines are IL-6, transforming growth factor (TGF-β), TNF-α, and IL-23, they activate STAT proteins, suppress apoptosis, and contribute to EMT." (PMID 37298889, 2023). "Meanwhile, inhibiting IL-6/STAT3 suppressed tumor cell growth and enhanced the sensitivity to antitumor drugs." (PMID 37404767, 2023). "Through a comprehensive exploration of the intricate interactions between IL-6 and the tumor microenvironment, this review highlights the need for a nuanced comprehension of IL-6 signaling in HCC." (PMID 37892997, 2023).
tumor (continued). "In OC, IL-6 has a significant role in the development of tumor growth, angiogenesis, and tumor myeloid cell infiltration." (PMID 37298230, 2023). "Inflammatory markers like high-sensitivity C reactive protein (hs-CRP), interleukin-10 (IL-10), interleukin-6 (IL-6), and tumor necrosis factor-alpha (TNF-α) reflect the chronic inflammation associated with tumor initiation and progression." (PMID 37764678, 2023). "GBM-microglia crosstalk via GM-CSF, IL-6 and G-CSF cytokines led to the increase of total glutamate level in the tumor microenvironment." (PMID 37468961, 2023). "It has been demonstrated that M1 macrophages expressed high levels of CD86, MHC II and B7 and mediated anti-tumor effects by secreting high-level cytokines (such as IL-12, IL-23, IL-1 and IL-6) and chemokines (MCP-1, CCL3, CXCL9, CXCL10, etc.)." (PMID 37762054, 2023). "Although the tumor growth effect of IL-6 is well-known and the application of anti-IL-6 receptor antibodies to cancer treatment has been attempted, there are few reports showing clear therapeutic effects." (PMID 36764954, 2023). "High expression of IL-6 and IL-8 correlated with the malignancy and metastasis of CMGTs, and therefore can be used as candidate biomarkers for tumor diagnosis." (PMID 36693957, 2023). "In vivo, IL-6 or IL6-R knockdown in tumor cells significantly increased survival in intracranial T3359 GSC models." (PMID 38030881, 2023). "Accompanied with tumour growth, the expression of IL‐6 was decreased in myeloid cell‐depleted WT mice, but was increased to some extent in myeloid cell‐depleted KO mice, compared with the nondepleted KO mice." (PMID 36419386, 2023). "ICAF, with low ACTA2 expression and high IL6 secretion, can be activated by paracrine factors secreted from tumor cells." (PMID 36900272, 2023). "Anti-IL-6 treatment alone increased the expression of stimulatory cytokines (IL-7 and IL-15) in MDSCs compared to the tumor-bearing control." (PMID 37108179, 2023). "TGF-β-induced Jagged1 amplifies this cycle by encouraging osteoblasts to produce tumor growth-promoting IL-6." (PMID 37440925, 2023). "Our work therefore suggests IL-6/ERK pathway as a potential target for enhancement of IFN-I-involved anti-tumor therapies." (PMID 36726024, 2023). "In this context, the levels of GM‐CSF, TNF‐α, IFN‐γ, IL‐1β, IL‐2, IL‐4, IL‐6, IL‐10, and IL‐13 in the peripheral blood of H22 tumor‐bearing mice were detected." (PMID 36043445, 2023). "The downstream pathway of STAT3 activated by IL-6 is also believed to be closely related to the proliferation, metastasis, and drug resistance of tumor." (PMID 37404767, 2023). "IL-6 is an inflammatory molecule that is highly expressed in tumor tissues and closely related to tumor cell proliferation." (PMID 37693915, 2023). "A poor prognosis can be associated with elevated levels of markers including C-reactive protein (CRP) and interleukin-6 (IL-6), which indicate systemic inflammation and link it to tumor aggressiveness and decreased overall survival." (PMID 37892820, 2023). "This strongly suggests that factors secreted by the tumor (e.g., IL6) or the interaction with the tumor environment contribute to the development of cancer cachexia." (PMID 36536236, 2023). "In another study, the overactivation of the IL-6/JAK/STAT3 pathway was found to promote tumor proliferation and invasion while suppressing anti-tumor immune responses." (PMID 37874419, 2023). "Fibroblasts from cancers, also known as cancer-associated fibroblasts (CAFs), differ from normal colonic MF (N-MFs) and support tumor-promoting inflammation, in part due to increased IL-6 secretion." (PMID 37185128, 2023). "This leads to (i) the recruitment of myeloid cells and MDSCs, which promote angiogenesis and suppress tumor immunity; and (ii) increased paracrine IL-6 production, known to increase tumor growth and survival." (PMID 36766689, 2023).
tumor (continued). "In contrast, the percentage of IL-6 secretion on enriched B cells decreased after the addition of tumor cell supernatant (last panel)." (PMID 37035195, 2023). "There was a significant increase in the number of CD4+ T cells and Tregs in the IL-6-depleted tumors indicating that the tumor cell derived increase in IL-6 secretion following Kindlin-1 loss can drive changes in Tregs in vivo." (PMID 36883731, 2023). "Here, iron is not only required for proliferation and cell cycle progression, but also in the production and release of intereluikin-6 (IL-6), which in turn promotes the upregulation of MMPs and the tumor invasion." (PMID 38033861, 2023). "IL-6 is a key regulator of inflammation via the JAK/STAT signaling pathway and IL-6 levels are associated with tumor stage, metastasis, and survival in CRC." (PMID 37958363, 2023). "We also showed that the nutraceutical resveratrol (RV) contrasts the oncogenic activities of IL-6 in the tumor microenvironment, acting as a potent inducer of autophagy and modulator of the transcriptome and epigenome." (PMID 36675246, 2023). "-Enhances TAM infiltration and polarization towards an anti-tumour phenotype.-Reduces IL-6 and CD206 expression in macrophages." (PMID 37894344, 2023). "The patients described illustrate the potential of serum IL-6, IL-8 and IL-10 for tumour monitoring in ALK + NSCLC." (PMID 37120670, 2023). "We demonstrated that CAFs induced TILs and TAMs within the TME, into an immunosuppressed state via IL-6 to promote tumor growth and explored a mechanism of IL-6-mediated immunosuppression by CAFs." (PMID 36764954, 2023). "Increased circulating IL‐6 levels resulted from elevated Il‐6 mRNA expression in cancer cells (9.5‐fold), tumour tissue (19‐fold), m.qu." (PMID 36351437, 2023). "CAFs attract Tregs and decrease CD8+ T cells infiltration into TME by secreting TGF-β and IL-6, thus interfering with tumor-directed immune response." (PMID 37064113, 2023). "GSEA also showed that IL-6 was upregulated when KLRB1 was downregulated, and IL-6 played an important role in tumor proliferation, metastasis, and chemotherapy resistance." (PMID 37520246, 2023). "M2 macrophages release epidermal growth factor, chemokines (such as CCL24and CCL22), and cytokines (such as TNF-α and IL-6) that directly promote tumor growth and metastasis and promote tumor progression." (PMID 37153586, 2023). "In the macrophage-MG-63 co-culture, the IL-10/IL-6 ratio decreased under the effect of mifamurtide both in macrophages and in tumor cells." (PMID 37835437, 2023). "It is a cytokine with potent anti-inflammatory properties by repressing the expression of inflammatory cytokines, such as TNF-α, IL-6, and IL-1 and is considered one of the most crucial immunosuppressive cytokines in tumor progression." (PMID 36835413, 2023). "An increased level of IL-6 production was identified as a tumor-promoting factor that affects inflammatory milieu and Th2 immune cell response." (PMID 37068081, 2023). "For example, CAF-secreted IL-6 enhances tumor cells’ epithelial–mesenchymal transition (EMT) via the activation of the Janus kinase 2/signal transducers and activators of the transcription 3 (JAK2/STAT3) pathway in GC." (PMID 37173977, 2023). "With the increase of IL-6, the abundance of tumor-infiltrated monocytes/macrophages and M2 macrophages increased after purity adjustment (monocytes/macrophages: P < 0.001, M2 macrophages: P < 0.001)." (PMID 37124547, 2023). "Higher IL-6 levels are correlated with higher tumor stage and disease-positive lymph nodes in HNSCC patients." (PMID 37849764, 2023). "IL-6, as a tumor promoting cytokine, triggers the Janus kinase (JAK) associated with the receptor, stimulating STAT3 phosphorylation and activation." (PMID 37035153, 2023). "In fact, IL-6 is one of the most important cytokines during tumorigenesis and metastasis, as it provides the tumor cells with the ability to escape cell death thus promoting tumor cell survival." (PMID 37275882, 2023).
tumor (continued). "They cause this effect through high expression of microvasculature signature genes and IL-6, along with their intimate interaction with ICC cells via the IL-6/IL-6R pathway, which in turn modulate tumor epigenetic alterations." (PMID 38239853, 2023). "Pro-inflammatory cytokines and chemokines, such as IL-6, IL-8, IL-1β, and TNF-α, can activate stromal cells, including CAFs and tumor-associated macrophages (TAMs)." (PMID 37760801, 2023). "A combination of an IL-6 inhibitor and anti-PD-L1 resulted in increased cytotoxic T cell infiltration and impaired tumour progression in the PDAC KPC-Brca2 mouse model." (PMID 37240052, 2023). "We found that the TGF-β and PDGF secreted by the tumor cells activated the fibroblasts, which increased their proliferation and IL-6 secretion." (PMID 37173963, 2023). "In many cancers, elevated level of serum IL-6 concentration largely correlates with tumor burden, chemo-resistance and poor clinical outcome." (PMID 38304256, 2023). "This positive feedback can produce chemotaxis of macrophages, and then produce TNF-α, resulting in increased IL-6 produced by tumor cells." (PMID 37151385, 2023). "It is believed that these two cell subtypes contribute to tumor progression, through the increase in IL-6, IL-10, and transforming growth factor β (TGF-β)." (PMID 36831674, 2023). "By secreting TGF-β, CCL2, CCL5, IL-6 etc., CAFs recruit immunosuppressive cells into the tumor stroma, which contributes to cancer metastasis and progression." (PMID 36843593, 2023). "While the M1 macrophages produce TNF-α, IL-6, and chemokines that maintain the inflammatory environment in the tumor, the M2 macrophages promote angiogenesis, growth, and metastasis of tumor tissue." (PMID 36937317, 2023). "TAMs are usually found to exhibit a tumor-promoting phenotype by producing immune suppressive cytokines such as IL-6, IL-10, and TGF-β, and they represent a large population of cells with immunosuppressive function in TME." (PMID 38239396, 2023). "ATC cells produce IL-6, which promotes tumor progression through M2 macrophage activation through signal transducers and activators of transcription (STAT) 3 signaling." (PMID 38250858, 2023). "A protumorigenic TME is saturated with several supporting tumor growth cytokines like interleukin (IL)-4, IL-6, and IL-10 as well as transforming growth factor (TGF)-β, interferon (IFN)-γ, and chemokines such as chemokine (C-C motif) ligand 2 (CCL2)." (PMID 38033495, 2023). "IL‐6 plays an important role in inflammation and leads to a secretion of both pro‐inflammatory and immunosuppressive factors in tumor cells and to the promotion of anti‐apoptosis, angiogenesis, and invasion." (PMID 36250429, 2023). "CAFs can secrete specific biological factors such as EGF, TGF-β, and IL6 to facilitate tumor malignant phenotype, including tumor neovascularization and immune escape, leading to tumor deterioration." (PMID 36755806, 2023). "We, therefore, conclude that the down-regulation of Il6 through Ccne1-depletion in HSCs is significantly involved in the reduced tumor burden of DEN/CCl4-treated Ccne1ΔHSC mice." (PMID 37620309, 2023). "Collectively, ENO1 orchestrated the IL-6 secretion of macrophages via tumor cell-derived lactic acid." (PMID 36614179, 2023). "We dissect the pro-tumorigenic effects of IL-6, including its impact on tumor growth, angiogenesis, and metastasis." (PMID 37892997, 2023). "For example, utilizing minimally invasive surgical approaches such as laparoscopy or robotic access for tumor removal operations reduces the circulating levels of IL-6 post-operatively, indicating a reduced level of systemic inflammation." (PMID 37426669, 2023). "It was also shown that CAFs strongly mediated tumor angiogenesis by secreting immunomodulatory and pro-angiogenic cytokines and chemokines, such as IL-4, IL-6, IL-8, TNF-α, TGF-β, VEGF, and SDF-1." (PMID 37686315, 2023).
tumor (continued). "As in the primary tumor, we also report that select M1 macrophage markers were reduced with emodin in wounded mice; emodin‐wounded mice exhibited reduced expression of IL‐6 (p = 0.0188) and a reduction in IL‐1β (p = 0.1193) compared to that of PBS." (PMID 37821408, 2023). "Common cytokines include TNF-α, IL-6, IL-8, and IL-10, which have the effect of promoting tumor invasion, growth, and angiogenesis." (PMID 37398678, 2023). "In striking contrast to BMDMs stimulated with LPS and IFN-γ, CDDO-Me increased TNFα (p < 0.0001) and IL-6 (p < 0.001) mRNA ~4-fold in WT tumor-educated BMDMs." (PMID 36670978, 2023). "Mast cells can generate trypsin, TNF, IL-1, IL-6, and other factors to boost anti-tumor inflammatory responses, stimulate tumor cell apoptosis, and suppress cancer cell invasion." (PMID 37719863, 2023). "Some of the proteins with elevated expression in TSC2‐ cells have previously been linked to mTORC1‐driven tumours in TSC, including HIF‐1α, MMPs, VE‐cadherin, IL‐6 and VEGF." (PMID 37337371, 2023). "Previously, we demonstrated that CAFs contribute to tumor growth by inducing tumor immunosuppression via IL-6 using in vivo experimental models." (PMID 36764954, 2023). "Elevated IL-1β and IL-6 expression in both tumor types indicated improved anti-tumor immunity with RT and combination treatment." (PMID 37242761, 2023). "Doxorubicin treatment inhibited PDAC tumor growth in IL-6 knock-out mice or wild-type mice receiving combination treatment with doxorubicin and IL-6 receptor antibodies." (PMID 36672405, 2023). "Aberrant expression of IL-6/STAT3 has also been shown to contribute to tumor aggressiveness and lower survival in CRC patients and AOM/DSS-induced CAC model mice 13-15." (PMID 37771783, 2023). "Our group has previously developed particles capable of removing small inorganic substances from whole blood, such as cytokines (interleukin-6, IL-6), lipopolysaccharides, digoxin and lead or single tumor cells." (PMID 37108680, 2023). "We showed that immunomodulatory drug treatment changed the tumor‐immune landscape and reduced the expression of immunosuppressive (IL‐6) and tumor growth‐promoting (IL‐8) cytokines." (PMID 36417691, 2023). "CD11b+Ly6G+ neutrophils produce IL-17 in tumor-bearing mice which promotes tumor growth through an IL-6-Stat3 signaling pathway." (PMID 37376417, 2023). "IL-6 is a multifunctional cytokine and an adipokine that clearly has both tumor-promoting and pro-inflammatory effects." (PMID 36835413, 2023). "Potential strategies for development of novel therapies would be either to target CAF-derived tumor promotion and immunosuppressive ligands, such as IL-6 and TGFβ, or to inhibit subtype-specific signaling pathways that would destroy specific CAF populations." (PMID 36835352, 2023). "The whole complex influence of IL-6 on tumor growth can become the basis of the purposefulness of carrying out various therapeutic actions." (PMID 36873124, 2023). "This suggested that IL-6 and IL-8 expression were closely related to tumor metastasis and the degree of malignant CMGTs." (PMID 36693957, 2023). "In agreement, Panx1 gene expression was positively correlated with the expression of IL-6 in LUAD tumor tissues." (PMID 37385076, 2023). "Correspondingly, the inflammatory factors of IL-1β, TNF-α, and IL-6 were increased in the MD@SA hydrogel group, offering a robust immune environment to restrict tumor regrowth." (PMID 37981704, 2023). "In a study investigating in vitro cytokine production, tumour-infiltrating lymphocytes produced a higher amount of IL1β and IL6 compared to peripheral blood leukocytes in OSCC patients." (PMID 36900301, 2023). "Subsequently, CAF can alter the tumor microenvironment by secreting IL-1β, IL-6, and IL-8, thereby enhancing the migration of OS cells." (PMID 37990331, 2023). "In support of this, SIK1 and SIK3 were shown to control IL-6 production in tumor cells and IL-6 and IL-1β production in Raw264.7 macrophages." (PMID 37140993, 2023).